PGR (progesterone receptor)
Diseases named in the same sentence as PGR in open-access papers (continued):
Sharing a sentence is not in itself a finding about the gene and the disease.
tumor (continued). "At immunohistochemistry, tumor cells showed a diffuse and strong staining for desmin, smooth muscle actin (SMA), oestrogen receptor and progesterone receptor." (PMID 29191211, 2017). "Immunohistochemically, tumour cells showed positive immunostaining with CD56, CD10, β-catenin, progesterone receptor and synaptophysin focally." (PMID 29187952, 2017). "Immunohistochemically, the tumor cells stained positively for vimentin, desmin, CD34, ER, and PgR and negatively for S-100, EMA, CK19, CD99, HMB45, and α-smooth muscle actin." (PMID 28831707, 2017). "Estrogen and progesterone receptor (ER and PR), HER2/ERBB2, and Ki67 expression levels together with tumor–node-metastasis (TNM) staging are the parameters used to stratify patients and guide therapeutic decisions." (PMID 26527623, 2016). "Sequenom MassARRAY was used for genotyping, and immunohistochemistry was performed to detect estrogen receptor (ER), progesterone receptor (PR), and human epidermal growth factor receptor 2 (HER-2) expression in tumor tissue." (PMID 27768589, 2016). "PDX tumors were stained for the most common prognostic markers, i.e. Estrogen (ER), Progesterone (PgR), HER2 receptors and Ki67, to assess the epithelial origin of the tumor, its correspondence with the patient tissue and its proliferative index." (PMID 27779108, 2016). "The tumor was positive for vimentin, CD10, α1-antichymotrypsin, α1-antitrypsin, β-catenin, neuron-specific enolase, synaptophysin, and progesterone receptor." (PMID 30631811, 2016). "Estrogen receptor (ER), progesterone receptor (PR), and human epithelial growth factor receptor 2 (HER2) are standard clinical tumor markers for determining the appropriate therapy for breast cancer patients." (PMID 27806114, 2016). "Clinicopathological factors at the time of initial operation, such as age, menopausal status, progesterone receptor expression, HER2 status, tumor grade and Ki-67, were compared between the disease-free group and the late recurrence group." (PMID 27388210, 2016). "Breast cancer patients are subtyped based on the estrogen receptor (ER), progesterone receptor (PR), and/or ERBB2 (HER2) status of the tumor." (PMID 27472462, 2016). "The expression of GLI1, Shh and NF-κB correlated with clinico-pathological variables including histological type, tumor grade, tumor size, lymph node metastasis, and EGFR, ErbB2, estrogen receptor (ER) and progesterone receptor (PR) expression." (PMID 26843616, 2016). "Women with BC having high and low DRC levels were further stratified by receptor status (estrogen receptor (ER), progesterone receptor (PR), and human epidermal growth factor receptor 2 (HER2)) and tumor grade." (PMID 27271599, 2016). "The PAM50 qRT-PCR assay was used to: a) assess tumor gene expression levels for ESR1, PGR, ERBB2, and 10 proliferation genes and b) classify tumors into intrinsic subtype (Luminal A, Luminal B, Basal-like, HER2-enriched, Normal-like)." (PMID 25884832, 2015). "Histopathological examination revealed an extensively hyalinized tumor with sparse collections of cells that were immunopositive for both cytokeratin and GFAP, and immunonegative for EMA and progesterone receptor." (PMID 26155457, 2015). "In tumor cells, the interaction between FGFR2, the progesterone receptor and STAT5 in the nucleus after FGF2 and medroxyprogesterone acetate (MPA) treatment has been associated with increased gene transcription and cell proliferation." (PMID 25970615, 2015). "In the ER+/PgR-/HER2- group, the ER percentage ranged from 1% to 100% (median, 71.8%), and the tumours of 22 patients expressed ER at levels <10%, whereas the PgR percentage ranged from 0% to 15% (median, 3.3%)." (PMID 25938238, 2015). "Immunohistochemically, the tumour cells displayed expression of pan-cytokeratin AE3, progesterone receptor, Wilms’ tumour protein (WT1), and PAX8 (Paired box gene 8)." (PMID 26197800, 2015).
tumor (continued). "Immunohistochemical examination of the tumour cells displayed expression of pan-cytokeratin AE3, estrogen- and progesterone receptor, Wilms’ tumor protein (WT1), and PAX8 (Paired box gene 8)." (PMID 26197800, 2015). "Estrogen receptor (ER), progesterone receptor (PgR), and human epithelial growth factor receptor 2 (HER2) are recognized as common clinical markers for tumor growth and progression, and indicators for determining appropriate therapy for BC patients." (PMID 27275301, 2015). "Profiling studies of primary breast tumors have revealed differential miRNA expression according to estrogen receptor (ER)/progesterone receptor (PR) or human epidermal growth factor receptor 2 (HER2) status and different tumor stages." (PMID 26080807, 2015). "On immunostaining, the tumor cells were positive of CD10, CD56, β-catenin, and progesterone receptor as well asα1-antitrypsin and vimentin." (PMID 26599966, 2015). "Discordance between primary tumor and MBC tissue biopsies occur at rates of around 10%–30% for ER and 20%–50% for PgR, with losses being more common than gains." (PMID 24670368, 2014). "The significantly higher percentage of tumours overexpressing BCL-2 was also found in LA and LB than in HER2+ and TN cancer immunophenotypes, identified on the basis of ER, PgR, HER2 and Ki-67 expression according to St." (PMID 25005788, 2014). "This challenges the currently used factors, such as lymph node involvement, tumor size, age, histological grade, human epidermal growth factor receptor 2 (HER2), Ki67, and estrogen (ER) and progesterone receptor (PgR) status." (PMID 23560250, 2013). "Quantitative PCR (qPCR) was performed to verify the expression of breast cancer-related genes (ERα, ErbB2, progesterone receptor (PR), and BRCA1) in each tumor cell lines." (PMID 23140372, 2012). "In the pT1a-pT1b tumours a lower incidence of prognostic biological factors associated with poor prognosis was observed: ER-negative status (12.7% vs 18.5%; p = 0.01), ER and PgR negative status (11.9% vs 17.9%; p = 0.01), and HER2-positive status (12.2% vs 18.7%; p = 0.006)." (PMID 22545982, 2012). "The tumor was staged as T2N1M0 and was estrogen receptor (ER) and progesterone receptor (PR) positive." (PMID 22867429, 2012). "The positive correlation of ERE transcriptional activity with PgR protein suggests that our Ad-ERE-GFP assay reliably reflects ERE transcriptional activity and tumor malignancy as ER functional target." (PMID 23342282, 2012). "Five of them analyzed one to four markers (including ER, progesterone receptor (PR), HER2, and/or Ki67) in a series ranging from 798 to 3,329 tumor samples." (PMID 22044691, 2011). "BCL2, ER, progesterone receptor (PR) and human epidermal growth factor receptor 2 (HER2) levels were determined in all tumours." (PMID 20664598, 2010). "The expression levels of S100 proteins were correlated with current clinical-pathological parameters which included age, tumor size, nodal status, immuno-cytochemical presence of HER-2, oestrogen receptors, progesterone receptor, and Ki67." (PMID 20815901, 2010). "Immunohistochemistry for estrogen receptor (ER-alpha), progesterone receptor (PR), human epidermal growth factor receptor 2 (HER-2/neu) and Ki-67 was performed in IELs and adjacent tumor tissues." (PMID 20412586, 2010). "Current opinion supports reassessment of estrogen receptor (ER), progesterone receptor (PR), and human epidermal growth factor type 2 (HER2) receptor in tumor tissue at the time of diagnosis of relapse to tailor appropriate therapy for each patient." (PMID 21059212, 2010). "In EGF100642, 17% of HER2-positive tumours were ER positive, whereas 43% were ER positive in EGF104911; PgR positive was detected in 15% and 35%, respectively." (PMID 19844234, 2009).
tumor (continued). "Our univariate Cox regression analysis demonstrated that tumor size, lymph node status, metastasis, grade, stage, ER status, PgR status, and HER2 status except tumor TNBC subgroup were the prognostic factors for 5-year DFS, in contrast to comparable series." (PMID 19534825, 2009). "In a multivariate analysis including traditional prognostic factors (age, menopausal status, tumour size, grade and ESR1 and PGR mRNA levels), NCOR2 mRNA levels were significantly associated with a favourable MFS (median, HR=0.68, P=0.006) and OS." (PMID 19904269, 2009). "Patients who have ER-positive tumours with unfavourable characteristics, such as HER-2 positivity, PgR negativity or nodal positivity, are likely to be selected for immediate AI therapy." (PMID 17892469, 2007). "ER-positive tumours fell into 2 subdivisions; subsets A and B both expressing luminal cytokeratins 8/18 but showing differential expression of HER2, c-Myc and PGR." (PMID 16595007, 2006). "The variables considered for this analysis were: grading of tumours, tumour size, lymph node involvement, tumour staging (following AJCC guidelines) and oestrogen and progesterone receptor levels." (PMID 15054465, 2004). "PgR level was significantly inversely related to EGFR activity (r=−0.28, P=0.001) and tumour size (clinical, P=0.002, r=−0.21 and pathological P=0.013, r=−0.18)." (PMID 12085248, 2002). "Losses at both loci were correlated with different histological types, age, tumour size, lymph node status, grading and steroid hormone receptor expression, [SHR: oestrogen receptor (ER), progesterone receptor (PgR)]." (PMID 8630282, 1996). "Immunohistochemically, tumor cells were androgen receptor and Forkhead box protein A1-positive and estrogen- and progesterone receptor-negative, with a Ki-67 index of approximately 30%." (PMID 41913897, 2026). "IHC revealed a positivity of the tumor cells for BerEp4, AE1/AE3, GATA‐3, Androgen Receptor (AR, 10%), CAM5.2, Estrogen Receptor (ER, 70%), Ki67 with a score of 10% and Progesterone Receptor (PR, 10%), negativity for TTF‐1, GCDFP‐15, HER‐2, HBME‐1, and Calretinin." (PMID 41239938, 2026). "Targeted immunohistochemistry showed tumor cell positivity for cytokeratin, nuclear beta-catenin, CD56, dot-like CD99, progesterone receptor (focal), and aberrant focal CD31 expression, with negativity for ERG and other vascular markers, confirming the diagnosis of SPN." (PMID 41859616, 2026). "On the other hand, the cells were negative for both ER and PgR, in contrast with the patient’s tumor tissue, which was positive for both." (PMID 39878900, 2025). "Spatial transcriptomics and scRNA-seq demonstrated the robust expression of estrogen receptor 1 (ESR1) and progesterone receptor (PGR) in fibroids with significant involvement of the ERK1/ERK2 pathway in mediating hormonal effects and promoting tumor progression." (PMID 39936948, 2025). "For the 31 patients who did not achieve pCR, we analyzed the changes in tumor expression of ER, PgR, and the Ki67 index before and after neoadjuvant therapy." (PMID 40687942, 2025). "MT1 expression has been studied in all breast cancer types and its association has been examined against multiple tumor characteristics: estrogen receptor (ER), progesterone receptor (PR), human epidermal growth factor receptor 2 (HER2), Ki67, and the tumor grade, to name a few." (PMID 40305352, 2025).
tumor (continued). "Immunohistochemical analyses depicted that the tumor was positive for estrogen receptor, progesterone receptor, desmin, and α-smooth muscle actin, but negative for S100." (PMID 40527829, 2025). "However, the evaluation of estrogen receptor (ER), progesterone receptor (PR), and human epidermal growth factor receptor-2 (HER-2) status in the tumor cells is also helpful in classification." (PMID 40844548, 2025). "Significant correlations were found with age > 50 years (P = 1.37E−04), high tumor grade (P = 0.002), Ki67 ≥ 20% (P = 8.64E−05), ER-negative status (P = 1.93E−13), and PgR-negative status (P = 2.99E−10)." (PMID 40128415, 2025). "Postoperative pathology revealed the recurrent tumor was consistent with breast origin, lobular in nature, ER > 66%, progesterone receptor (PR) 34% to 66%, HER2 IHC of +2, with a negative silver in situ hybridization (SISH) result." (PMID 39996881, 2025). "Among LumA-assigned cases, admixture was associated with slightly higher estrogen receptor positivity but lower progesterone receptor (PR) positivity and estrogen receptor–related gene expression and higher HER2 positivity, tumor size, grade, and tumor–node–metastasis stage." (PMID 39740059, 2025). "Immunohistochemistry demonstrated tumor positivity for vimentin, epithelial membrane antigen (EMA), progesterone receptor (PgR), and thyroid transcription factor-1 (TTF-1) and negativity for cytokeratin and B-cell lymphoma-2 (Bcl-2), with a Ki-67 proliferation index of <1%." (PMID 40265140, 2025). "Aggressive triple-negative (TN) and HER2-positive tumors exhibited greater tumor-to-background ratios than estrogen receptor (ER) and progesterone receptor (PR)-positive tumors." (PMID 40507930, 2025). "Immunohistochemical analysis showed that the tumor was negative for the estrogen receptor (ER), progesterone receptor (PgR), and HER2, confirming the diagnosis of triple‐negative breast cancer (TNBC)." (PMID 41031282, 2025). "In TNBC, a tumour that does not express oestrogen receptor (ER), progesterone receptor (PR), and HER2, elevated PD-L1 expression is frequently detected." (PMID 41284319, 2025). "The tumor cells were negative for estrogen receptor, progesterone receptor, and other neuroendocrine markers (chromogranin and neuron-specific enolase)." (PMID 41431020, 2025). "The neoplasm in our case was diffusely negative for progesterone receptor expression, consistent with its higher grade, malignant behavior, and poor outcome." (PMID 41327755, 2025). "Oestrogen and/or progesterone receptor staining was observed in 16 of 29 cases (2–30% of tumour cells), and all were HER2 negative or low (0–1+)." (PMID 41195654, 2025). "Tumours not expressing the oestrogen receptor (ER) or progesterone receptor (PR) and have no human epidermal growth factor receptor 2 (HER2; also referred to by its gene name ERBB2) amplification are classified as triple-negative breast cancer (TNBC)." (PMID 40136651, 2025). "Many of these parameters, such as the immunohistochemistry (IHC) expression of estrogen receptor (ER) and progesterone receptor (PgR), HER2 status, tumor stage, lymph node involvement, and Ki67%, are already widely recognized for their prognostic and predictive roles." (PMID 40717834, 2025). "A sample is considered negative for ER or PgR if < 1% or 0% of tumor cell nuclei are immunoreactive." (PMID 39129012, 2024). "If ER (not PgR), 1% to 10% of tumor cell nuclei are immunoreactive, the sample are reported as ER Low Positive." (PMID 39129012, 2024). "Of particular note, while both ESR1 and PGR showed higher expression in non-recurrent tumours in the first 5 years of follow-up in METABRIC, neither showed a significant difference after 10 years in either METABRIC or VLR." (PMID 38709373, 2024). "Additionally, NK-92 cells significantly reduced the viability of PgR-expressing U87MG-luc cells, and compared to Abi treatment alone, the combination with Prog further enhanced NK-92-mediated tumor suppression." (PMID 39103871, 2024).
tumor (continued). "Smaller tumours showing biologically favourable characteristics (oestrogen/progesterone receptor positive, HER2 negative tumours) are associated with almost 100% survival at 10 years." (PMID 38310343, 2024). "The tumor was hormone receptor-negative for Progesterone Receptor (PR-) but tested positive for Estrogen Receptor (ER+) and Human Epidermal Growth Factor Receptor 2 (HER2+)." (PMID 39795579, 2024). "There was a significant negative correlation between miR-18a and PGR transcript, an estrogen-regulated gene (Pearson’s correlation co-efficient: −0.31, p = 0.02) in these tumours." (PMID 38786043, 2024). "Fbxo22 negativity was correlated with negative PgR status but not with high Ki-67 positivity, lymph node involvement, or tumor grade." (PMID 38180699, 2024). "Since PAQR4 was identified recently as a novel tumour suppressor, we analysed its expression, even though it is not a recognised progesterone receptor." (PMID 39464509, 2024). "This study starts from the perspective of the endocrine system to find key factors regulating macropinocytosis and elucidates that the progesterone receptor can elevate the macropinocytosis level in PDAC cells, thereby maintaining the growth advantage of tumor cells." (PMID 38424455, 2024). "Additionally, estrogen and progesterone receptor expression donates a more favorable biology of the tumor, while vascular endothelial growth factor (VEGF) promotes tumor progression through angiogenesis." (PMID 39845255, 2024). "Second, we did not report the results stratified by tumor type including estrogen and progesterone receptor because there were few studies reporting results classified by tumor type distinctly." (PMID 38436219, 2024). "The tumor turned out to be estrogen and progesterone receptor-positive, i.e., ER+, PR+, and Her2/neu-negative, and had a Ki-67 labeling index of 40%." (PMID 39682607, 2024). "This was supported by the observation that high PTK7 mRNA expression was significantly associated with higher NPI groups, ER- or PgR-negative tumours, and HER2-positive tumours in the METABRIC cohort." (PMID 39335176, 2024). "Expression of the transporter was frequently observed in large and aggressive tumours and was markedly expressed in patients diagnosed with negative oestrogen and progesterone receptor subtypes." (PMID 36982217, 2023). "TK1 is associated with aggressive tumor features such as advanced stage, high grade, ER/PgR negative, tumor necrosis, and vascular invasion, suggesting its central role as a BC proliferation marker." (PMID 37767092, 2023). "Core needle biopsy and immunohistochemistry (IHC) staining showed that the tumor was ER-positive (70%+), progesterone receptor (PR)-negative, HER2-negative (1+), and Ki67-positive (20%+)." (PMID 37120151, 2023). "The breast cancer prognosis and treatment response are affected by a variety of factors, including the presence of the estrogen receptor (ER), the progesterone receptor (PR), human epidermal growth factor receptor 2 (HER2/neu), tumor histological grade, type, and size, and the lymph node metastasis." (PMID 37469704, 2023). "Grade, tumor size, lymph node involvement, metastasis, ductal or lobular subtype, progesterone receptor status, or proliferation index (Ki-67) did not correlate with exercise-induced immune cell mobilization." (PMID 37085562, 2023). "Finally, we compared expression between groups defined by clinical factors (tumor size and type, node status, molecular subtype, ERBB2, and progesterone receptor." (PMID 37491786, 2023).